AR (androgen receptor)
Diseases named in the same sentence as AR in open-access papers (continued):
Sharing a sentence is not in itself a finding about the gene and the disease.
cancer (continued). "Some studies show that in certain cancer cells, AR may regulate cell survival and inflammatory responses through NF-κB activation." (PMID 39335190, 2024). "In support of our speculation, SREBF1 was evidenced to operate as a key metabolic effector of AR to orchestrate de novo lipid synthesis in cancer cells." (PMID 38369486, 2024). "For instance, palmitoyl-acyltransferase ZDHHC7 showed a negative association with DNA damage and hormone AR pathways in seven and eight cancer types, respectively." (PMID 37978524, 2023). "This shows that both transfected TG2 forms can modulate AR expression, however, the endogenous truncated TG2 form, by specific accumulation in the nucleus most likely leads to specific lowering of AR expression, thus conferring growth advantage to the cancer cells in this way." (PMID 37160910, 2023). "Thus, androgen deprivation therapy (ADT), the first-line therapy that initially leads to cancer regression, aims to eliminate AR signaling." (PMID 36937411, 2023). "To investigate whether the AR affects cancer progression, we examined the mRNA expression of AR in various bladder cell lines and observed that AR expression was lower in BCa cell lines than in bladder fibroblast cell lines." (PMID 36800968, 2023). "Therefore, 5α-reductase inhibitors must play a crucial therapeutic role to suppress cancer development, improve prognosis, and independently modulate AR activity." (PMID 36800968, 2023). "Herein, lncRNA IGFL2-AS1 interacts with the AR mRNA to exert its cancer promoting function." (PMID 37037853, 2023). "However, even when cancer initially responds to AR axis suppression, virtually all patients eventually progress to a state known as castration-resistant prostate cancer (CRPC)." (PMID 37509723, 2023). "In the prednisone combination treatment groups, radium-223 and abiraterone may prevent PSA production by killing cancer cells and inhibiting AR signaling, respectively." (PMID 37627143, 2023). "Additionally, it has been demonstrated that the expression of certain proteins is related to the response of androgen deprivation therapy (ADT) treatment in some cancer tissues, including androgen receptor (AR)-V7." (PMID 37742230, 2023). "To examine whether dutasteride, a 5α-reductase inhibitor, affected AR-induced cancer progression, we overexpressed AR using an AR lentiviral vector in T24 BCa cells." (PMID 36800968, 2023). "As both androgen deprivation therapy and AR inhibitors can suppress DNA damage repair genes, concurrent treatment with enzalutamide could make cancer cells more vulnerable to radium-223-induced DNA double-strand breaks." (PMID 36768509, 2023). "KIFC1 may be an actionable cancer-cell-specific target for the AR-low TNBC subpopulation and could aid in alleviating racial disparities in TNBC outcomes." (PMID 38003261, 2023). "Interestingly, a weak, but positive, correlation between MYB and AR (r = 0.15, p = 0.00074) was also reported at the transcripts level in publicly available The Cancer Genome Atlas dataset." (PMID 38089573, 2023). "For instance, AR-42 and belinostat were found significantly associated with PIK3CA mutation in HNSC + LUSC (here considered jointly because of known molecular similarities of the cancer types), in BRCA, and in LUAD cancer types." (PMID 37095494, 2023). "Androgen receptor (AR) is a classical oncogenic factor in many types of cancer." (PMID 36594084, 2023). "AR signaling has been suggested as a contributing factor in other cancers." (PMID 37626712, 2023). "However, experiments have found that AR can interfere with ER binding to estrogen-related elements and inhibit the proliferative effect of ER, thereby promoting cancer cell apoptosis." (PMID 36929229, 2023). "The fact that Au-AR pep-PROTAC inhibits AR-positive cancer cells suggests that AR is rapidly destroyed at the protein level, as other small molecules that target AR have similarly demonstrated total suppression of AR-positive cancer cells." (PMID 37631305, 2023).
cancer (continued). "AR has also been recognized for its importance in cancer etiology and progression." (PMID 37272305, 2023). "Similarly, miR-22, which is an androgen receptor (AR) cistrome member, suppresses process of cancer cells such as LNCaP or PC3 in PCa." (PMID 37501932, 2023). "Additionally, fisetin interferes with the ligand binding domain of androgen receptor (AR), resulting in a reduction in cancer cell growth." (PMID 37626424, 2023). "However, a subset of tRNA halves are constitutively expressed in androgen receptor (AR)- or estrogen receptor (ER)-positive cancer cells even though they are processed by angiogenin." (PMID 37430089, 2023). "Similarly, AR was expressed in 100% (6/6) of cases with CS but had ER and PR expression in 67% and 50% of the cancers respectively." (PMID 37725629, 2023). "The androgen receptor (AR) is a member of the nuclear hormone receptor family of transcription factors that regulates a canonical gene expression program involved in prostate homeostasis and, upon deregulation, cancer development." (PMID 37751307, 2023). "MAP3K7 was also demonstrated to promote the degradation of AR protein levels in conjunction with a TNFa and NFKB-mediated inflammatory response, indicating that cancers with this Ch6q deletion may have elevated AR and reduced inflammation." (PMID 38201511, 2023). "The use of docetaxel in mCSPC is likely more efficacious at targeting AR-independent cancer cells early, compared to its use in mCRPC, where these cancer cells may have had opportunities to develop resistance." (PMID 37185445, 2023). "However, simvastatin reduced AR expression in enzalutamide-resistant cancer cells alone or in combination with enzalutamide." (PMID 36769263, 2023). "Several factors (i.e., phenotype changes) contribute to the plasticity of cancer cells, such as mutations in the androgen receptor and overexpression of the protein ABCG2, which in turn contributes to the production of chemical castration-resistant cancer cells." (PMID 38131796, 2023). "Further studies are needed to determine whether auraptene exerts anti-cancer effects in CRPC when used either alone or in combination with available AR targeting agents." (PMID 37958994, 2023). "Furthermore, the use of catalytic Top2 inhibitors such as ICRF-193 or T60/T633 in combination with enzalutamide has demonstrated a synergistic effect that blocks AR signaling and cancer cell replication." (PMID 36678591, 2023). "However, when agonists activate the AR, it suppresses estrogen-driven cancer growth by altering the genomic distribution of the ER and essential coactivators such as p300 and steroid receptor coactivator 3 (SRC-3)." (PMID 37681860, 2023). "ATP-citrate lyase (ACLY), acetyl-CoA carboxylase (ACC), fatty acid synthase (FASN), stearoyl-CoA desaturase-1 (SCD1), 3-hydroxy-3-methyl-glutaryl-CoA reductase (HMGCR), and squalene epoxidase (SQLE) are overexpressed in cancer cells and are under the transcriptional control of the AR." (PMID 36674430, 2023). "Activation of the AR mediates cancer progression through the interaction of integrins." (PMID 37681860, 2023). "Complex AR gene rearrangements displayed co-evolution with AR copy number due to AR being captured on double-minute or extrachromosomal DNA (ecDNA), which are large circular DNA molecules in cancer cells known to harbor amplified oncogenes." (PMID 37636316, 2023). "CAF–conditioned medium promotes DHEA-induced AR activation by increasing 3βHSD1 in cancer cells." (PMID 37009898, 2023). "For example, AR expression in cancer cells is said to be negatively correlated with tumor grade, which means that high delivery efficiency may not be achieved when targeting cancer cells in the advanced clinical stage." (PMID 37239005, 2023). "For example, it is unknown whether initiating hormonal therapy as the first-line treatment is better than chemotherapy in androgen receptor (AR) positive cancers." (PMID 37799960, 2023).
cancer (continued). "During the G1-S checkpoint, CDK4/6 activation by the AR axis contributes to cancer cell proliferation; among the mechanisms of resistance to NHA, the upregulation of cyclin D1 (whose association with CDK4/6 is crucial for the transition from G1 to S phase) was described." (PMID 37894312, 2023). "This demonstrated that increased AR could act as a cancer suppressor and improve prognosis by activating cell death, which might be focus for future research." (PMID 38090588, 2023). "Therefore, many studies have focused on how AR is overexpressed, modified by mutation, or differentially spliced to drive the AR signaling axis under ADT and promote cancer growth." (PMID 35018219, 2022). "In contrast to the association of pTyr705-Stat3 with an AR+/ERβ+/MUC1+ epithelial phenotype, pSer727-Stat3 is associated with a basal cell phenotype, again analogous to the mesenchymal phenotype induced by pSer727-Stat3 in other cancers." (PMID 36017196, 2022). "It was proposed that AR expression increased in cells that were grown in suspension and that AR expression possibly favored a cancer stem cell (CSC)-like population, which could be therapeutically targeted by antiandrogens such as enzalutamide." (PMID 36497214, 2022). "Also, AR was shown to act as ligand-dependent TFs that confer to resistance against AR-targeted cancer therapies under hypoxic conditions." (PMID 36064320, 2022). "AR signaling in the stroma of the microenvironment has been shown to affect cancer cells." (PMID 36551674, 2022). "In these studies, the stage and status of cancer differ, and the ranges of AR, AR/ER, and ratio of AR expression to PR expression (AR/PR) differ as well, which could lead to opposite conclusions." (PMID 36556209, 2022). "The cancer cells expressed strong diffuse nuclear expression for AR and NKX3.1." (PMID 36643868, 2022). "In addition, different compounds have been tested for cancer cachexia atrophy, among which: androgen receptor modulators, bimagrumab, ghrelin, and growth hormone secretagogue receptor synthetic agonists." (PMID 36010642, 2022). "Moreover, overexpression of miR-99b-5p targets/inhibits AR-mTOR axis, subsequently initiating cell apoptosis and sensitizing docetaxel-induced cytotoxicity in various cancers." (PMID 36077039, 2022). "An anastrozole (aromatase inhibitor) arm study showed that the significant decrease in the glandular expression of ERα and AR could restrict the proliferation of cancer cell." (PMID 35886904, 2022). "However, despite its importance in cancer biology and therapy, how Src-mediated Tyr-534 phosphorylation of AR is regulated remains incompletely understood." (PMID 35595729, 2022). "ARCC-4 had better anti-proliferative effects in AR mutant cancers, whereas enzalutamide failed." (PMID 35370971, 2022). "Several other signallings such as PI3K/Akt or reprogrammed AR signalling may also be adopted by cancer cells." (PMID 35832549, 2022). "The role of androgens and AR might vary depending on cancer cell types and/or on the level of expression of other steroid hormone receptors." (PMID 35052843, 2022). "As a result, dysregulation of AR-mediated signals may be an important factor in the development of many tumors and cancers." (PMID 36235203, 2022). "Moreover, it has been seen that BPA did not impair androgen effects in normal prostate cell lines, but acted as an antiandrogen in cancer cells when AR splicing forms were expressed." (PMID 35163140, 2022). "AR signaling pathway plays an essential role in prostate development and cancer." (PMID 35841025, 2022). "AR is a core signaling pathway during prostate development, cancer formation, and drug resistance." (PMID 35841025, 2022). "Similarly, during carcinogenesis, the presence of AR in stromal fibroblasts promotes the proliferation of (epithelial) cancer cells both in vitro and in vivo." (PMID 37435460, 2022).
cancer (continued). "The activation of androgen receptor (AR)-mediated signaling is an essential route for regulating PCa cell growth and proliferation; thereby, alterations in this cascade hold a great influence on cancer progression." (PMID 36176747, 2022). "Thus, disseminated cancer cells with an inactive or mitigated AR-signaling axis can still colonize and grow in target organs." (PMID 36561929, 2022). "Subsequent investigations were extended to ER-/PR-/AR+ cancer cell models, and demonstrated that AR signaling, induced by DHT, directly upregulates let-7a expression, which in turn reduces the levels of its target oncogenes CMYC and KRAS impairing cell proliferation." (PMID 36111296, 2022). "Later stages of invasion and metastasis in EC maybe partly due to inactivation of cancer suppressive AR signaling." (PMID 35814433, 2022). "The activation of AR signaling will promote cancer development." (PMID 35053220, 2022). "Furthermore, the peptidyl‐prolyl cis/trans isomerase activity of FKBP51 was found to be required for AR dimer formation and cancer cell growth." (PMID 34057812, 2022). "We show by experimental and computational methods that androgen receptor blockade upregulates inflammatory pathways, which may finally trigger survival mechanisms of cancer cells." (PMID 36551650, 2022). "Finally, physalins A and B interact with receptors that are overexpressed in some cancers, such as the androgen receptor (AR)." (PMID 35450054, 2022). "As observed, AR and its ligand, DHT, affect the expression of known and unknown androgen-regulated genes associated with cancer, many of which are also BCa-related genes." (PMID 35568821, 2022). "A study from Gustafsson’s group suggested that ERβ could suppress cancer cell proliferation by repressing AR signaling." (PMID 35966880, 2022). "Anti-ER or AR approaches thus seem as effective options for such type of cancers." (PMID 35812730, 2022). "The currently used drug, enzulamide, inhibits the action of AR by interacting with the LBD domain of the receptor, which is a therapy failure, with cancer cells expressing AR variants that do not contain this domain in their structure." (PMID 35055079, 2022). "In addition, AR is involved in the proliferation and migration of cancer cells and chemotherapeutic drug resistance." (PMID 35886904, 2022). "AR positivity is generally higher in luminal cancers (ER/PgR-positive cancers), and it may be reasonable that mucinous cancers with higher ER/PgR positivity have higher AR positivity." (PMID 36553136, 2022). "In addition to elevated expression, increased AR tyrosine phosphorylation, activation and signaling are also critical for promotion of cancer progression." (PMID 35595729, 2022). "Both of these studies attribute the sex bias in cancer to AR-mediated regulation of Tcf7/TCF1 in CD8+ T cells and the subsequent differentiation to dysfunctional T cells; however, the former ascribed a positive regulatory role while the latter a negative regulatory role." (PMID 36337733, 2022). "Yet another recent study found that an oncogenic lncRNA KDM4A-AS1, which notably increased in CRPC cell lines and cancer tissues and was associated with unfavorable outcomes, promoted the stability of the USP14-AR-FL/AR-Vs complex and the de-ubiquitination of AR/AR-Vs." (PMID 36012111, 2022). "Abnormal AR signaling has been reported in cancer development." (PMID 35960413, 2022). "High androgen levels have also been associated with an increased risk of OC initiation, and literature data have suggested that androgen receptor (AR) signaling might play an important role in cancer growth)." (PMID 36230510, 2022). "These opposing roles of AR may allow for the targeted development of new and better therapies for specific cancer types." (PMID 35517428, 2022).
cancer (continued). "AR plays an important role on steroid-dependent cancers, especially in pre- and post-menopausal." (PMID 35886904, 2022). "Interestingly, recent studies have indicated a relationship between the AR and microRNA (miRNA) crosstalk and cancer progression." (PMID 35163477, 2022). "Four and a half LIM domains protein 2 (FHL2) which is known to play role in development and progression of different types of cancer via activation of androgen receptor (AR or NR3C4), Wnt/β-catenin pathway or several genes was demonstrated as target of miR-195-5p." (PMID 35281110, 2022). "Furthermore, in these types of cancers, abnormal miRNA interactions with AR have also been described." (PMID 35163477, 2022). "In addition to those “AR-dependent” castration-resistant adenocarcinomas, a subset of patients was found to progress in AR-independent cancer biology, with short-term responses to hormone therapy, early and widespread metastases, and poor outcomes." (PMID 35669435, 2022). "Binding of androgen to the AR initiates the signal of cell growth and proliferation in cancer." (PMID 35740392, 2022). "The Akt kinase pathway is regulated by FKBP5, and the FKBP5/AR complex may affect the sensitivity of cancer cells to paclitaxel by regulating the expression of the txr gene." (PMID 35886904, 2022). "This study identified the AR gene regulated by has-miR-942-3p which may depend on the MAPK/ERK signaling pathway to promote the proliferation of cancer cells." (PMID 36135175, 2022). "It was speculated that NRIP might promote cancer cell proliferation by enhancing the transcriptional activity of AR." (PMID 35886904, 2022). "Furthermore, the PPIase activity of FKBP51 was found to be required for AR dimer formation and cancer cell growth." (PMID 34057812, 2022). "Androgen acts on prostate normal or cancer cells through its receptor AR." (PMID 36362304, 2022). "Besides, androgens and AR have been shown to enhance cancer cell migration, epithelial–mesenchymal transition (EMT), and the number of EC stem cells." (PMID 36358974, 2022). "The PPIase activity of FKBP51 is essential for cancer cell proliferation and AR dimer formation." (PMID 34057812, 2022). "It has been well documented, for example, Tyr-534 phosphorylation of AR by Src, an oncogenic tyrosine kinase, is critical for AR activation, nuclear translocation, transactivation of downstream target genes and consequently cancer progression." (PMID 35595729, 2022). "Indeed, accumulating evidence suggests that, besides AR signaling, other pathways play a role for the development of androgen-independent cancer progression." (PMID 36551650, 2022). "Further, using cell-based assays on in vitro models of PCa and clinical data, we demonstrated that FK866 has the potential to be repurposed as novel candidate drugs for treating lethal PCa, particularly in PCa models of Taxane and/or AR-inhibitor drug resistance and cancer stemness." (PMID 36497496, 2022). "Cancer cells can co-opt key homeostatic stress responses, including adaptive changes in mRNA translation that contribute to cell survival and therapy resistance, but little is known about roles for AR mRNA and regulation of its translation during ARPI stress." (PMID 34939643, 2022). "In addition, inhibition of androgen receptors, which are potential targets of androgen-receptor-positive cancer cells, by LEE has been reported." (PMID 36077241, 2022). "In addition, the PPIase activity of FKBP51 was essential for cancer cell proliferation as well as AR dimer formation." (PMID 34057812, 2022). "Enzalutamide as an AR inhibitor can inhibit cancer cell growth in uterine leiomyosarcoma." (PMID 35886904, 2022).